CYGB (cytoglobin)
Diseases named in the same sentence as CYGB in open-access papers (continued):
Sharing a sentence is not in itself a finding about the gene and the disease.
cancer (30 papers, 2006 to 2024). A tumor composed of atypical neoplastic, often pleomorphic cells that invade other tissues. "In a CYGB-deficient mouse model, we found that 67% of mice aged 1–2 years spontaneously exhibit abnormalities and cancer development in multiple organs, including the liver, lungs, lymph nodes, and heart." (PMID 35504863, 2022). "Cellular and biochemical studies show that cytoglobin expression results in changes to phenotype associated with cancer progression including: increased cellular proliferation, motility and cell cycle progression." (PMID 33441751, 2021). "The research on the association between human cancer and globins (e.g., MB, cytoglobin, CYGB) has grown in the last years." (PMID 34440755, 2021). "In the same line, loss of expression of cytoglobin in cancer cells occurs due to loss of heterozygosity (LOH) and also by epigenetic regulation via hypermethylation of CpG islands in the Cygb gene promoter region." (PMID 26339645, 2015). "The abnormal expression of CYGB has been linked to various human cancers." (PMID 39227479, 2024). "Additionally, multiple cancer-associated pathways were enriched in the CYGB-deficient G361-shCYGB cell line compared to G361-shCTR." (PMID 36009267, 2022). "It was further suggested that the promoter of CYGB was methylated, causing the silencing of CYGB expression, and that the restoration of CYGB could inhibit cancer cell growth." (PMID 33611811, 2021). "Aberrant expression of CYGB has also been linked to different human cancers." (PMID 30545372, 2018). "This confirms that promoter methylation participates in the suppression of CYGB expression across a wide range of cancers." (PMID 39227479, 2024). "Altogether, we show that silencing of CYGB expression modulates cancer therapy sensitivity via regulation of ferroptosis and pyroptosis cell death signaling pathways." (PMID 36009267, 2022). "CYGB-positive cells were more abundant in carcinoma areas than in ECM-rich fibrotic septum in all samples." (PMID 35504863, 2022). "Mechanistically, CYGB‐overexpressing cancer cells were more sensitive to ferroptosis inducers, such as RSL3 and erastin, due to the increase in YAP1 expression." (PMID 33611811, 2021). "In the present study, we demonstrated that CYGB inhibited cancer cell growth, decreased mitochondrial function and increased lipid peroxidation." (PMID 33611811, 2021). "The results furtherly suggested that ZDHHC1 inhibits glucose metabolism in cancer cells at least in part through the CYGB-mediated glucose metabolism pathway." (PMID 32863941, 2020). "Apart from GPD1L and CYGB, miR-210-3p can target several other genes in cancers, such as FGFRL136, SIN3A37, and EphrinA338." (PMID 32908121, 2020). "This review provides an overview of the proposed role of cytoglobin and explores its potential functional role as a biomarker for cancer and other diseases." (PMID 26339645, 2015). "Further, the levels of oxygen-utilizing hemoproteins, such as cytoglobin, were dramatically increased in cancer cells." (PMID 23704904, 2013). "CYGB, a member of the globin family that contains a heme group (which includes iron), plays an important role as a tumor suppressor due to its differential concentration in cancer cells and subsequent scavenging of RONS." (PMID 37759771, 2023). "CYGB is also thought to be involved in the development of cancer." (PMID 36112670, 2023). "We also wonder whether PSCs secrete factors other than CYGB that regulate the proliferation of cancer cells." (PMID 35504863, 2022). "Moreover, increased cardiolipin levels were observed in cells expressing cytoglobin involved in cancer progression." (PMID 36338962, 2022). "Moreover, CYGB significantly increased the sensitivity of cancer cells to RSL3‐ and erastin‐induced ferroptotic cell death." (PMID 33611811, 2021). "In conclusion, our data shows that cytoglobin expression results in important phenotypic changes that could be exploited by cancer cells in vivo to facilitate disease progression." (PMID 33441751, 2021).
cancer (continued). "CYGB is downregulated in many human cancers due to promoter hypermethylation." (PMID 32908121, 2020). "Based on these data together with our previous studies using Cygb-deficient mice, we hypothesize that CYGB is a potent regulator of HSC activation and is involved in all aspects of hepatic inflammation, fibrosis and cancer development." (PMID 30552362, 2018). "To explore the possibility of whether some types of cancer are enriched in CYGB, we screened for CYGB using several cancer cell lines of diverse origins." (PMID 24722418, 2014). "Cytoglobin is a recently described, intracellular globin whose role in cancer is as yet unclear but may be related to detoxification of oxygen free radicals (Trent, III and Hargrove, 2002)." (PMID 16449996, 2006). "In general, the combination of CYGB mutation and disulfide bond formation between Cys38 and Cys83 through CAP-generated RONS increased the enzymatic activity of CYGB as a cytoprotective protein, which could be beneficial in cancer therapy." (PMID 37759771, 2023). "In addition to its anti-oxidation effect on ROS, CYGB has been found to be closely related to cancer, but whether CYGB is an oncogene or a tumor suppressor gene is controversial." (PMID 35397613, 2022). "In addition to its gas-bindingability, CYGB is relevant to hepatic inflammation, fibrosis, and cancer because ofits anti-oxidative properties; however, the regulation of CYGB geneexpression remains unknown." (PMID 28916723, 2017). "Cytoglobin (CYGB) and glutathione peroxidase 4 (GPX4) are two members of this protein family whose modification by CAP-generated RONS can be effective in cancer therapy, and they have been studied at the atomic scale using MD simulations." (PMID 37759771, 2023). "Perhaps heme directly regulates the expression of cytoglobin and cytochrome c, while a heme-independent mechanism contributes to the increased levels of CYP1B1 and Cox-2 in cancer cells." (PMID 23704904, 2013). "Thus, it is likely CYGB is one of the key factors downstream of ZDHHC1 in suppressing glucose metabolism and thereby cancer cell growth." (PMID 32863941, 2020). "The rescue experiment further verified that the knock-down of CYGB could partially reverse the ability of ZDHHC1 overexpression to inhibit the proliferation and induce apoptosis in cancer cell lines." (PMID 32863941, 2020). "Nevertheless, without a comprehensive outlook of the molecular and functional role of the globin, it will be most unlikely to consider cytoglobin as a biomarker for early detection of cancer or as a therapeutic option." (PMID 26339645, 2015). "Our results show that, in agreement with previous findings, over expression of cytoglobin in cancer cell lines afforded protection from chemically-induced oxidative stress but this was only observed at non-physiological concentrations of cytoglobin." (PMID 22359545, 2012). "Their high expression level of CYGB might be attributable to the gene amplification, a process by which the subchromosomal portions of the genome increase in copy number, which has been frequently observed in many human cancers but not in normal cells." (PMID 24722418, 2014).
infection (1 paper, 2023). The state of being infected such as from the introduction of a foreign agent such as serum, vaccine, antigenic substance or organism. "A further three non-infection associated genes (CYGB, IRF6 and elastin microfibril interfacer 2 (EMILIN2)) were assessed." (PMID 37276213, 2023).
CYGB also shares sentences with these, for which no sentence is quoted: non-alcoholic steatohepatitis (3 papers); adenocarcinoma (2); Cirrhosis (2); heart hypertrophy (2); Liver Diseases (2); adenoma (1); Barrett’s metaplasia (1); cholestasis (1); chronic hepatitis (1); chronic kidney disease (1); ciliopathies (1); colitis (1); colon adenocarcinoma (1); cyst (1); cystic kidney disease (1); diabetes (1); diabetic nephropathy (1); esophageal adenocarcinoma (1); esophageal cancer (1); head and neck tumours (1); intestinal tumour (1); invasive ductal breast carcinoma (1); invasive lobular breast carcinoma (1); Kidney Cyst (1); liver inflammation (1); lung adenocarcinoma (1); lymph node metastases (1); lymphoma (1); metastatic melanoma (1); renal clear cell carcinoma (1).
A further 2 diseases each share a sentence with CYGB in 1 paper.